CCND1 (cyclin D1)
Diseases named in the same sentence as CCND1 in open-access papers (continued):
Sharing a sentence is not in itself a finding about the gene and the disease.
tumor (continued). "It regulates Cyclin D1 expression and may help maintain tumor stem cells, as evidenced by its promotion of mammosphere formation in vitro." (PMID 40080721, 2025). "In hepatocellular carcinoma cells, overexpression of Prx2 increased the TOPflash reporter activity, whereas knockdown of Prx2 reduced cyclin D1 and c-Myc expression, induced cellular senescence as shown by increased β-galactosidase activity, and inhibited tumor growth in xenograft models." (PMID 41009046, 2025). "In addition, a previous study reported that BAP18 is upregulated in NSCLC tissues and promotes tumor cell proliferation by transcriptionally activating CCND1 and CCND2, suggesting a potential oncogenic role." (PMID 40818609, 2025). "Aberrant Wnt signaling leads to the stabilization and the nuclear accumulation of β-catenin, which interacts with TCF/LEF to drive expression of the proto-oncogenes such as CCND1 (encoding Cyclin D1) and MYC, fueling uncontrolled cell proliferation and tumor growth." (PMID 40773107, 2025). "Concerning Cyclin D1 expression in relation to clinicopathological parameters, there were statistically significant correlations between Cyclin D1 expression and tumor site (P = 0.009), local recurrence (P = 0.019), distant metastasis (P = 0.024), and lymph nodes involvement (P = 0.02)." (PMID 41189865, 2025). "In squamous cell carcinoma (OSCC), elevated CREPT expression was associated with cyclin D1 and c-MYC expression and correlated with pronounced stromal interactions and aggressive tumor behavior, highlighting the crucial role of CREPT in promoting aggressive phenotypes." (PMID 40723282, 2025). "In contrast, cyclin D1–overexpressing tumor cells that are ATM proficient may be highly vulnerable to combined POLΘ and ATM inhibition." (PMID 40608419, 2025). "In addition, since the immunostaining was positive for β-catenin, a common hallmark of SPN, as well as cyclin D1 and 11% positive for MIB-1, she was diagnosed with low-grade malignant SPN, despite the large size of the tumor." (PMID 39903574, 2025). "It has been found that IRSp53 is tyrosine phosphorylated at multiple sites in response to EGFR stimulation, and knocking down of IRSp53 diminished cell proliferation in cells that v-Src transformed and tumor formation in mice through p-AKT/p-Stat3/cyclin D1 signaling pathway." (PMID 41200137, 2025). "In vivo, CDH17 suppression resulted in 80–95% tumour growth suppression (Mean Difference (MD) = −96.67, 95% CI: [−144.35, −48.98], p < 0.0001), with immunohistochemistry confirming cytoplasmic β-catenin sequestration and lower cyclin D1 levels." (PMID 41155133, 2025). "Furthermore, now in addition to our previously reported MOA of OTI-611, we have uncovered OTI-611’s effects on Cyclin D1 nuclear dynamics, its induction of G1 cell cycle arrest, and its ability to reduce tumor cell proliferation." (PMID 40072047, 2025). "We aim to explore whether the effect of 66CTG on regulating xenograft growth and the c-Myc/Cyclin D1 signaling pathway in tumor tissues will be enhanced with increased 66CTG expression levels." (PMID 40628713, 2025). "Moreover, the lack of experimental verification limits the interpretation of the biological role of CCND1 in tumor progression." (PMID 39940659, 2025). "Moreover, differences in cluster counts between surface markers (CD81, EpCAM, PD-L1) and the intravesicular marker Cyclin D1 also correlated with tumor stage." (PMID 41008614, 2025). "Furthermore, CDK2 is crucial for cyclin D1-mediated centrosome overduplication, which impacts to chromosomal instability and supports tumor progression." (PMID 39929880, 2025).
tumor (continued). "Therefore, overexpression of cyclin D1 disrupts normal checkpoint control, facilitating tumor aggressiveness and poor differentiation." (PMID 41541922, 2025). "Notably, the knockdown of miR-181 resulted in the reduced spheroid formation and tumor initiation capability, accompanied by the downregulation of cyclin D1 (CCND1) and epithelial cell adhesion molecule (TACSTD1) levels." (PMID 41514651, 2025). "Among epithelial populations, we identified tumor cells (expressing Cd44, Ccnd1, Plau, Krt7), luminal alveolar (AV) cells (expressing Kit, Ehf, Csn3, Ltf), luminal hormone-sensing (HS) cells (expressing Prlr, Esr1, Pgr), and myoepithelial cells (expressing Myh11, Mylk, Myome1)." (PMID 41332581, 2025). "In addition, Cyclin D1 can accumulate in both the nucleus and cytoplasm in tumor cells to induce its oncogenic roles." (PMID 40072047, 2025). "Consequently, CCND1 gene expression, a key downstream target of β‐catenin, was significantly upregulated in tumor tissues compared to peritumoral tissues (p = 0.02213), and its expression correlated positively with β‐catenin accumulation (r = 0.42703)." (PMID 40344393, 2025). "Overexpression of cyclin D1 leads to excessive cell proliferation, resulting in rapid tumor growth." (PMID 40869149, 2025). "Cyclin D1-dependent mechanisms can promote tumor invasiveness and high proliferative activity." (PMID 40303287, 2025). "Additionally, KIF5B-ALK fusion promotes the transition from the G1 to the S phase by activating cyclin-related proteins, such as cyclin D1, further facilitating tumor progression." (PMID 40852483, 2025). "Many studies suggest that the high expression of Cyclin D1 may be an important factor in promoting the resistance of tumor cells to chemotherapy drugs." (PMID 39712859, 2025). "While high expression is consistently associated with worse survival outcomes, the absence or low expression of Cyclin D1 appears to have variable effects, potentially influenced by differences in tumor biology, molecular subtypes, and methodological approaches across studies." (PMID 39940659, 2025). "Additionally, elevated ANO1 expression is accompanied by increased phosphorylation of ERK1/2, activating the MAPK/ERK pathway while upregulating Cyclin D1 expression, thereby facilitating the G1/S phase transition and promoting tumor cell proliferation." (PMID 40356890, 2025). "In addition to apoptosis-related markers, CA administration was associated with reduced expression of cell proliferation proteins, including PCNA and Cyclin D1, indicating potential suppression of tumor cell replication." (PMID 40453666, 2025). "Additionally, both mRNA and protein levels of cyclin D1 were significantly higher in HCC tumor tissues compared to adjacent normal tissues." (PMID 39866238, 2025). "When cyclin D1 is deregulated, through overexpression, accumulation, or inappropriate localization, it becomes an oncogene and contributes to genomic instability and tumor development." (PMID 40408472, 2025). "Moreover, statins induce cell cycle arrest at the G1 phase by suppressing cyclin D1 and upregulating p21, effectively halting tumor progression." (PMID 40387523, 2025).
tumor (continued). "Similarly, the prolonged activation of the LTF danger signal mirrors mechanisms observed in CRPC progression, where chronic NF-κB activation prevents tumor regression through AR/cyclin D1 maintenance." (PMID 40607016, 2025). "For evaluating possible impacts of the secretome of the hAMSCs on tumor growth plus progress via EGFR/c-Src/IRSp53/p-AKT/p-Stat3/cyclin D1 signaling pathway, first coculturing of HT-29 colon cancerous cells /hAMSCs was fulfilled for 72 h afterward, they underwent MTT assay." (PMID 41200137, 2025). "Recent advances have identified various biomarkers, such as Ki-67, Cyclin D1, Bmi-1, and EMT-related proteins, that enhance diagnostic accuracy and prognostic assessment, while emerging research into tumor mutational burden and metabolic pathways offers promising therapeutic targets." (PMID 41158948, 2025). "Notably, although CCND1 amplification in LUAD was estimated to occur relatively late in primary tumour evolution, it nevertheless occurred frequently before metastatic seeding consistent with a potential role in the metastatic transition." (PMID 40804524, 2025). "Furthermore, the highly expressed, tumor-specific targets c-myc and cyclin D1 in cells were also found to be downregulated following the action of AFC." (PMID 40308769, 2025). "Coordination of C-MYC with Cyclin D1 not only accelerates tumor formation but also may drive tumor progression to a more aggressive phenotype." (PMID 40224178, 2025). "P27Kip1 and cyclin D1 serve as critical regulators of cell cycle progression, and any abnormalities in their expression may impact cell division, potentially leading to tumor development." (PMID 40178080, 2025). "Our results suggest that nisin Z could be associated with the observed lower tumor burden in the middle section of the small intestine by decreasing cyclin D1 expression and thereby reducing tumor cell proliferation." (PMID 41051239, 2025). "Moreover, despite the tumor volumes appeared to be unaffected by SAFit, the transcript levels of CCND1 and TGF-β were decreased in SAFit treated-tumors." (PMID 40180895, 2025). "In addition to CCND1, rearrangements involving genes such as PIK3CA and EGFR are also implicated in OSCC pathophysiology, contributing to tumor progression and reduced therapeutic efficacy, thereby representing potential targets for novel treatment strategies." (PMID 40427514, 2025). "Our findings suggest that Asperglaucide may inhibit tumor development by interacting with CCND1 to regulate key signaling pathways, including the AGE-RAGE signaling pathway, the PI3K-Akt signaling pathway, and the AMPK signaling pathway." (PMID 40302810, 2025). "Thus, we showed that the injection of GBM cells overexpressing α-syn drastically lowers the tumor volume and reduces cyclin D1 levels in vivo model." (PMID 40108111, 2025). "Previous studies in solid tumors have suggested that tumors with CCND1 amplification may impede immune cells and have an immunosuppressive tumor microenvironment through mechanisms such as immune cell exclusion and exhaustion." (PMID 41159027, 2025). "Furthermore, NQO1 mRNA levels were elevated in PBMCs, while reductions in NF-κB and cyclin D1 expression were observed in tumor samples." (PMID 40732256, 2025). "Moreover, silencing cyclin D1 in HG-ESS led to dephosphorylation of RB1 and inhibited tumor growth, highlighting the role of cyclin D1 in cell cycle regulation." (PMID 40001568, 2025).
tumor (continued). "The inactivation of the tumor suppressive function of wild type pRb in ccRCC is likely due to the reported cyclin D1 overexpression, fueled by HIF activation, as well as the inactivation of CDK inhibitors, leading to phosphorylation-based inactivation of cell cycle control." (PMID 40240354, 2025). "At the molecular level, this response is linked to decreased expression of cyclin D1 and cyclin D3, inhibition of cyclin-dependent kinases (CDK2, CDK4), and downregulation of the PI3K/AKT pathway, which plays a central role in tumor survival and metastatic progression." (PMID 41303402, 2025). "miR-193a-3p activated CCND1, and quenched fluorescence and showed tumor suppressor function." (PMID 40061926, 2025). "Based on these data, we inferred that Con-A + SB-treated cells had significantly lower expression levels of proteins linked to tumor formation, such as JAK1, STAT3, PCNA, cyclin D1, along with evidence of G2/M phase arrest, as indicated by the downregulation of Cyclin B and Cdk1." (PMID 40350446, 2025). "Research has demonstrated that CCND1 serves as a biomarker for tumor phenotype and progression." (PMID 41395621, 2025). "The Polycladia crinita extract mediated its promising anticancerous action by enhancing apoptosis and mitigating inflammation via VEGF, Notch 1, NF-кB, IL-6, Cyclin D1, Caspase 9 and Caspase 3 expression/level, which manifested in promoting the total survival rate and the tumor volume decrease." (PMID 38469406, 2024). "Cyclin D1 expression showed a few faint positive tumor nuclei." (PMID 38396984, 2024). "This accumulation led to a decrease in cyclin D1 expression in tumor tissue." (PMID 40259961, 2024). "Interestingly, several studies have demonstrated that CDK4/6–cyclin D1 also regulates the function and development of immune cells in the tumor microenvironment." (PMID 39593745, 2024). "Our application of controlled, cellular-scale force suggests that cyclin D1 overexpression may adapt dividing cells to the mechanical burdens of the tumor environment." (PMID 38478555, 2024). "We aimed to determine whether the expression levels of the genes correlated to survival in MB patients (Trp53bp1, Bax, p21, Cyclin D1, Nanog, and Oct4) also influence the radiation response and can predict tumor reactions to irradiation." (PMID 39594660, 2024). "Similarly to the β-N model, we observed fewer tumor foci that were Myc-tag, GS/Ki67, and cyclin D1 positive in the responder animals." (PMID 39711542, 2024). "However, protein levels of cyclin D1, a proliferation-inducing protein, were higher in the tumor tissues of VDUP1 KO mice than in those of WT mice." (PMID 39272794, 2024). "Detailed information about the correlations between methylation and mRNA expression, the methylation difference between tumor and normal samples, and the overall survival difference between higher and lower methylation groups of CCND1 in the selected 13 cancers." (PMID 39188436, 2024). "Erianin may exert its anti-tumor effect in DDP-resistance LUAD cells by regulating the Wnt3/β-Catenin/Survivin/Bcl-2/Caspase3/Cyclin D1 axis." (PMID 39605083, 2024). "In addition, the downregulation of cyclin D1 and CDK4, which encode proteins that regulate the cell cycle, is associated with tumor progression." (PMID 38548549, 2024). "Likewise, during this process, cyclin D1 is overexpressed to potentially enhance tumor cell proliferation." (PMID 38571493, 2024). "Cyclin D1 promotes cell cycle progression from the G1 to the S phase, facilitating tumor growth." (PMID 39682631, 2024). "However, when cyclin D1 expression is high, cyclin D1 drives unchecked cell proliferation, promoting tumor growth, and it is central to the pathogenesis of cancer." (PMID 39518131, 2024).
tumor (continued). "Furthermore, Treating mice bearing SEC with free P. crinita extract (25, 50 mg/kg) revealed a sustainable decrease in Cyclin D1 protein values (31.5% and 52.3%, respectively), following the tumor control group." (PMID 38469406, 2024). "As referred before, cyclin D1 may facilitate tumor growth as a downstream effector of METTL16 in GC." (PMID 39009956, 2024). "Except for the CSNP-treated group, the expression of the tumor-promoting CCND1 gene was significantly (p ≤ 0.05) downregulated in all treated groups compared to the EST-untreated control group, The PL-CSNP + DXN-CSNP combination showed the highest downregulation (tenfold)." (PMID 38253759, 2024). "MORC3 deficiency downregulated the E-cadherin (CDH1) tumor suppressive gene and the keratin 14 (KRT14) epithelial differential marker but significantly upregulated the expression of oncogenic JUN, CCND1, CCND2, and CCN1 at the transcriptional level." (PMID 39329063, 2024). "Erianin may exerted its anti-tumor effect in DDP-resistant LUAD cells by regulating the Wnt3/β-Catenin/Survivin/Bcl-2/Caspase-3/Cyclin D1 axis." (PMID 39605083, 2024). "Similarly, the incidence of tumor development in FGF19/CCND1/sgTrp53 animals 10 months after HGT remained identical to that of FGF19 animals (n = 2/5, maximum of 1 tumor/liver)." (PMID 38228803, 2024). "Additionally, mRNA analysis revealed significant upregulation of the level of anti-apoptotic gene Bcl-XL and proliferation-inducing gene cyclin D1 in the tumor tissues of VDUP1 KO mice compared to those of WT mice." (PMID 39272794, 2024). "In the context, cyclin D1 gene expression decreased after treatments with P. crinita free extract (25, 50 mg/kg) and SeNPs loaded P. crinita extract (25, 50 mg/kg) by (13, 35, 50, and 71% decrease, respectively), compared to a tumor control group." (PMID 38469406, 2024). "Notably, the observed reduction in tumor-promoting markers such as β-catenin and cyclin D1, particularly in the context of LPS-induced carcinogenesis, underscores the therapeutic potential of FXR-targeted approaches." (PMID 38069256, 2023). "Thus, Ccnd1 promotes cell detachment, migration and invasion of normal and tumour cells independently of pRB status by interacting with cytoplasmic and membranous targets, such as filamin A, PACSIN, Ral GTPases and paxillin." (PMID 37684532, 2023). "Immunohistochemical staining (IHC) of tumor tissues showed that the changes in Cyclin D1, VEGF, and pAKT were similar to those in vitro results, indicating that the combination of Rh2 with radiation could improve the therapeutic efficacy." (PMID 37764996, 2023). "We also found the expression of Ccnd1 encoding Cyclin-D1, which promotes cell cycle progression, was downregulated in Clec7a−/− mice under both SPF and GF conditions, consistent with the suppression of tumor growth in Clec7a−/− mice." (PMID 36932082, 2023). "A transcriptional deficit of NF‐κB (nuclear factor kappa‐light‐chain‐enhancer of activated B cells) was substantiated by the downregulation of cyclin D1 and of the anti‐apoptotic Bcl2, in line with reduction in tumour cell proliferation and induction of apoptosis, respectively." (PMID 37390227, 2023). "Interestingly, CCND1 levels are significantly correlated with patient survival in a limited number of tumor types." (PMID 37081792, 2023). "Cyclin D1 (CCND1) is an effector gene that promotes tumor progression in a variety of cancers." (PMID 37340423, 2023). "Additionally, through the inhibition of TSP1 and co-expression with the vascular growth factor VEGF, CCND1 can promote angiogenesis, enabling tumour survival, growth, and metastasis." (PMID 37510349, 2023).